SLC26A2 (solute carrier family 26 member 2)
Diseases named in the same sentence as SLC26A2 in open-access papers (continued):
Sharing a sentence is not in itself a finding about the gene and the disease.
brachydactyly (1 paper, 2025). A disease characterized by the presence of brachydactyly, including syndromic and non-syndromic forms. "Genu valgum (knock-knee deformity) is a prevalent manifestation of SLC26A2-related MED and is often accompanied by mild brachydactyly." (PMID 40392407, 2025).
breast carcinoma (1 paper, 2016). "Four marker genes (ID4, SOSTDC1, SLC26A2, TNC) relevant to drug activity to cisplatin on breast cancer cells were derived from the signature genes for breast cancers." (PMID 26824188, 2016).
cleft palate (1 paper, 2021). Cleft palate is a fissure type embryopathy that affects the soft and hard palate to varying degrees. "Specific to skeletal dysplasia, pathogenic variants in genes encoding type II and XI collagen (COL2A1, COL11A1 and COL11A2), Filamin-A (FLNA), and the diastrophic sulfate transport protein (SLC26A2) are all well-known as being associated with cleft palate." (PMID 33446226, 2021).
disc degeneration (1 paper, 2019). "Our results also showed that several enzymes that catalyze the biosynthesis of sulfated glycosaminoglycans (GAGs) of proteoglycans, including CHST1, EXTL3 and SLC26A2, were differentially methylated in the advanced stage of human disc degeneration compared to those in the early stage." (PMID 31513634, 2019).
gastritis (1 paper, 2023). Inflammation of the stomach. "In this study, we screened 11 important lncRNAs (AFAP1-AS1, MIR155HG, LINC00472, and FAM201A) and mRNAs (CASP10, SLC26A2, TRIB1, BMP2K, SCAMP1, TNKS1BP1, and MBOAT2) according to the gene expression profiles of gastric epithelial tissues in different stages of Hp infection-induced gastritis." (PMID 37249580, 2023).
larynx carcinoma (1 paper, 2021). A primary or metastatic malignant neoplasm involving the larynx. "The migration experiments showed that miR-770-5p could partially reverse the effect of LINC02086 on the migration of larynx carcinoma cells, while SLC26A2 could weaken the effect of miR-770-5p on the migration of larynx carcinoma cells." (PMID 34130645, 2021).
patella dislocation (1 paper, 2022). "HOXB9 gene and SLC26A2 gene were found to be the possible pathogenic genes or related genes for patella dislocation." (PMID 35934709, 2022).
skeletal dysplasia (11 papers, 2009 to 2026). Any Mendelian diseases that affects growth and development of the skeleton. "Pathogenic variants in SLC26A2 lead to a wide spectrum of both lethal and non‐lethal skeletal dysplasia." (PMID 41554664, 2026). "Our findings not only demonstrated the efficacy of melatonin in ameliorating abnormal function and cell fate of SLC26A2-deficient chondrocytes in vitro but also underscored its role in partially alleviating the skeletal dysplasia seen in Col2a1-CreERT2; Slc26a2fl/fl mice." (PMID 39759111, 2025). "Indeed, the overlapping phenotypes in the spectrum of SLC26A2-associated skeletal dysplasias have been reported in the literature." (PMID 36140680, 2022). "Additionally, the Solute Carrier Family 26 Member 2 gene (SLC26A2) encodes for a protein that seems to modify sulphate transporting residual activity, and is associated with short body size and skeletal dysplasia." (PMID 35454235, 2022). "The first five have autosomal dominant inheritance, while variants in the SLC26A2 gene cause the autosomal recessive form (rMED or MED type 4) (OMIM: 226900), which demonstrates the milder clinical form within the spectrum of SLC26A2-associated skeletal dysplasia." (PMID 36140680, 2022). "Four variants were highlighted in four genes known to cause skeletal dysplasias, namely EBP, INPPL1, COL1A2, and SLC26A2, being the last two characterised by high in utero lethality." (PMID 41153384, 2025). "Subjects with SLC26A2-related skeletal dysplasia, born between 2000 and 2020, were identified from the Skeletal dysplasia registry and from hospital patient registry and their clinical and molecular data were reviewed." (PMID 34064542, 2021). "This included seven genes (LIFR, TMEM38B, PLS3, NANS, SLC26A2, ALX4, and PLS3) associated with skeletal dysplasia or bone disease, and four of them were ARE-containing genes with increased expression." (PMID 29727687, 2018). "Our Finnish pediatric cohort comprised 14 subjects with SLC26A2-related skeletal dysplasia; 75% of all subjects and 90% of those with the DTD phenotype were homozygous for the Finnish founder mutation and one was (compound) heterozygous for the founder mutation." (PMID 34064542, 2021). "The present data also provides an indication of a putative defect in GAG sulfation, which may lead to dramatic biological effects, as exemplified by mutations in PAPSS2, SLC26A2, gPAPP or SUMF1, all causing skeletal dysplasias." (PMID 19898608, 2009). "Mutations in SLC26A2 lead to a wide spectrum of both lethal and non-lethal skeletal dysplasia." (PMID 34064542, 2021).
cancer (4 papers, 2015 to 2024). A tumor composed of atypical neoplastic, often pleomorphic cells that invade other tissues. "Moreover, a recent study reported that SLC26A2 acts as an unusual mediator of TRAIL resistance, as the loss of SLC26A2 resensitizes cancer cells to TRAIL-mediated cell death." (PMID 38684689, 2024). "In sum, CXCL3, SLC7A5, SLC26A2, GART, and CCDC68 genes were differentially expressed in three or more cancer types." (PMID 29843204, 2019).
tumor (4 papers, 2022 to 2025). "Higher SLC26A2 expression in tumor tissues indicates a longer survival for patients with CRC." (PMID 36110947, 2022). "Consistent with the results from the datasets, the expression levels of ADH1C, SLC26A2, and NANS were substantially decreased in tumor tissues compared with those in the corresponding adjacent tissues (P<0.01)." (PMID 36110947, 2022). "The expression of ADH1C, SLC26A2, and NANS was determined in the TCGA-COADREAD dataset (n=689) and four large external cohorts (GSE106582, n=194; GSE31737, n=80; GSE117606, n=208; GSE74602, n=60), and the expression of the three genes were compared between tumor and control tissues." (PMID 36110947, 2022).
metabolic disorder (1 paper, 2012). "Interestingly, the metabolic disorder in Miniature Poodles appears to share more clinical signs with a spectrum of human disorders caused by SLC26A2 than with the mouse Slc13a1 model." (PMID 23300579, 2012).
SLC26A2 also shares sentences with these, for which no sentence is quoted: achondrogenesis type IB (7 papers); atelosteogenesis type II (5); Pendred syndrome (4); skeletal diseases (4); colorectal cancer (3); Congenital chloride diarrhea (2); infection (2); scoliosis (2); achondroplasia (1); asthenozoospermia (1); atelosteogenesis type (1); autosomal recessive deafness (1); bronchiectasis (1); camptomelic dysplasia (1); colitis (1); congenital chloride diarrhoea (1); cranioectodermal dysplasia (1); Crohn disease (1); cystic fibrosis (1); Ehlers-Danlos syndrome (1); Epiphyseal dysplasia (1); Hearing impairment (1); Hip dysplasia (1); Hyperoxaluria (1); hypothyroidism (1); irritable bowel syndrome (1); nephrocalcinosis (1); nephrolithiasis (1); neuroendocrine tumor (1); nodular goiter (1).
A further 3 diseases each share a sentence with SLC26A2 in 1 paper.